HMGB1 (high mobility group box 1)
Diseases named in the same sentence as HMGB1 in open-access papers (continued):
Sharing a sentence is not in itself a finding about the gene and the disease.
Cerebral ischemia (114 papers, 2010 to 2026). Restriction of arterial blood supply to the brain associated with insufficient oxygenation to support the metabolic requirements of the tissue. "Significantly, administration of anti-HMGB1-SA to t-MCAO rats dramatically reduced brain damage causedby cerebral ischemia/reperfusion." (PMID 37844138, 2023). "In the next section, function of PAD4 in cerebral ischemia, which is associated with NETosis–thrombosis interaction, will be addressed with special focus on the relationship with HMGB1." (PMID 32731558, 2020). "The duality of HMGB1 in cerebral ischemia have brought on challenges linked to the therapeutic translation." (PMID 33384585, 2020). "High mobility group box 1 is a key endogenous danger associated molecular pattern which acts as a mediator of neuroinflammation resulting from a variety of conditions such as cerebral ischemia-reperfusion, septic shock, and traumatic brain injury." (PMID 31258464, 2019). "This event, releases high-mobility group box 1 (HMGB1) and damage associated molecular patterns (DAMPs), which are well characterized in cerebral ischemia." (PMID 24961318, 2013). "After the onset of cerebral ischemia, dead cells and macrophages actively secrete DAMPs (damage-associated molecular patterns), which include high mobility group box 1 (HMGB1), s100, and ATP, and play a role in initiating immune responses after central nervous system injury." (PMID 40900923, 2025). "Moreover, HMGB1/NF-κB signaling has been widely reported in inflammation-associated acute injuries, including spared nerve injury, acute lung injury and cerebral ischemia–reperfusion injury." (PMID 32412059, 2020). "In accordance with this findings, haemorrhagic shock could cause a decrease blood flow to the brain and heart causing myocardial and cerebral ischemia thus releasing HMGB1." (PMID 32994992, 2020). "In addition, the NLRP3 inflammasome is associated with HMGB1 activation during cerebral ischemia." (PMID 33384585, 2020). "HMGB1 has good predictive value for cerebral ischemia–reperfusion injury in patients with ischemic stroke, which correlates with leukocyte infiltration, extensive cerebral infarction, and worsened prognosis." (PMID 38740617, 2025). "Inhibition of HMGB1 remote ischemic preconditioning and post-ischemic treatment reduced plasma HMGB1 levels and enhanced its neuroprotective effects against cerebral ischemia–reperfusion injury by inhibiting autophagic processes." (PMID 38740617, 2025). "HMGB1 was released in large quantities from neurons during acute injury induced by excitotoxicity and cerebral ischemia (1 h after MCAO)." (PMID 38740617, 2025). "Both Stress and cerebral ischemia synergistically increase HMGB1 levels in the serum and hippocampus, with activated microglia being the main source of its release." (PMID 40688353, 2025). "In cerebral ischemia, enriched lactate induces histone lactylation in high mobility group box 1 (HMGB1) and promotes HMGB1 expression." (PMID 40732225, 2025). "Another study indicates that high mobility group protein B1 (HMGB1), acting as an inflammatory mediator induced by cuproptosis, is rapidly released extracellularly post-cerebral ischemia." (PMID 40510202, 2025). "High-mobility group box 1 (HMGB1) emerges as a pivotal player in neuroinflammation after brain ischemia and ischemia–reperfusion." (PMID 38740617, 2025). "Intriguingly, hepatocytes and Kupffer cells in the liver displayed an unexpectedly rapid response to cerebral ischemia, inducing HMGB1 expression and upregulating hepcidin expression." (PMID 39349828, 2024). "Nevertheless, further investigation is warranted to delineate the potential contributions of these cell types to HMGB1 levels in cerebral ischemia." (PMID 39349828, 2024). "Ischemia and reperfusion injury, associated with the loss of HDAC 1 and 4, or cerebral ischemia and reperfusion injury associated with the loss of HDAC 4 and 5 were both associated with HMGB1 translocation or cellular release." (PMID 38673851, 2024).
Cerebral ischemia (continued). "In recent years, the high-mobility group box 1 (HMGB1)/receptor for advanced glycation end products (RAGE) signaling pathway has emerged as a promising target for therapeutic interventions in cerebral ischemia." (PMID 37829255, 2023). "The importance of HMGB1 and other factors, including IL-6, with respect to hepcidin induction after cerebral ischemia requires further study." (PMID 37907744, 2023). "During cerebral ischemia, HMGB1 is released from neurons, reactive microglia and reactive astrocytes upon primary injury, and then binds to specific receptors of microglia to further aggravate the secondary injury." (PMID 35415314, 2023). "In conclusion, engeletin strongly prevents focal cerebral ischemia via suppression of the HMGB1/TLR4/NF‐κB inflammatory network." (PMID 37132060, 2023). "(2020) observed that a large amount of released HMGB1 downregulates GLAST through TLR4 expression after cerebral ischemia, thereby inhibiting astrocyte glutamate clearance." (PMID 37062906, 2023). "These novel insights into the pathogenesis of cerebral ischemia highlight the potential of targeting the HMGB1/RAGE pathway with EA as a promising therapeutic strategy for this debilitating condition." (PMID 37829255, 2023). "Inhibition of the JAK2/STAT3 signaling pathway by using curcumin can reduce HMGB1 expression after cerebral ischemia." (PMID 37062906, 2023). "Parecoxib sodium was shown to reduce the expression of HMGB1 in a cerebral ischemia model, and hence, it plays a neuroprotective role." (PMID 36639747, 2023). "HP improves survival, motor function, and brain injury after cerebral ischemia by binding to HMGB1 and regulating macrophage/microglia polarization." (PMID 36959823, 2023). "The effects of FPS-ZM1 and electroacupuncture (EA) on activation of the HMGB1/RAGE signaling pathway after cerebral ischemia remain uncertain." (PMID 37829255, 2023). "Subsequent experiments involving intravenous injectionof anti-HMGB1-SA to t-MCAO rats dramatically reducedbrain damage induced by cerebral ischemia/reperfusion." (PMID 37844138, 2023). "High‐mobility group box1 (HMGB1) induces inflammatory injury, and emerging reports suggest that it is critical for brain ischemia reperfusion." (PMID 37132060, 2023). "A clinical study showed that the serum HMGB1 levels in patients with cerebral ischemia were higher than in healthy volunteers." (PMID 36133805, 2022). "This is the first report to clarify the mechanism via which Hp protects against cerebral ischemia by inhibiting systemic elevation of HMGB1." (PMID 35243897, 2022). "High systemic HMGB1 levels are known to be responsible for activation of macrophages/microglia after cerebral ischemia." (PMID 35243897, 2022). "HMGB1 influences neuroinflammatory responses to cerebral ischemic injury, which conduces to the pathogenesis of cerebral ischemia." (PMID 36081910, 2022). "A large amount of HMGB1 is released by necrotic cells and infiltrating macrophages after cerebral ischemia and triggers inflammatory processes, such as activation of macrophages/microglia." (PMID 35243897, 2022). "In this study, we identified that the mechanism via which Hp exerts its beneficial effect includes rapid binding to HMGB1, which prevents systemic elevation of HMGB1 after cerebral ischemia, decreases M1 macrophages/microglia, and suppresses brain damage." (PMID 35243897, 2022). "Meanwhile, we have confirmed that the level of brain HMGB1 after cerebral ischemia also increases more slowly than the plasma HMGB1 level." (PMID 35243897, 2022). "A study on cerebral ischemia in rats also postulates that HMGB-1 can upregulate the expression of MMP-9 although this mechanism has not been determined in the pancreas." (PMID 35041718, 2022). "We focused on systemic elevation of HMGB1 because it reflected the severity of functional outcomes and the increase of M1 macrophages/microglia after cerebral ischemia." (PMID 35243897, 2022).
Cerebral ischemia (continued). "HMGB1 (high‐mobility group box 1) is known to worsen the functional prognosis after cerebral ischemia." (PMID 35243897, 2022). "The gradual increase in systemic HMGB1 levels after the onset of cerebral ischemia occurs because of the release of HMGB1 from necrotic or damaged cells or from activated macrophages/monocytes." (PMID 35243897, 2022). "This study evaluated the effects of Hp on the neuroinflammation and brain damage induced by HMGB1 after cerebral ischemia." (PMID 35243897, 2022). "The HMGB1 release from neurons was evident after the brain ischemia/reperfusion or brain trauma in rats, indicating that HMGB1 was increased in both plasma and the CNS." (PMID 36275732, 2022). "In cerebral ischemia, HMGB1 is mainly released by dying neurons, and circulating HMGB1 levels correlate with ischemic brain damage." (PMID 34681935, 2021). "For example, MIAT inhibited high-mobility group box 1 (HMGB1) expression by competitively binding to miR-204-5p to regulate the injury of cerebral artery occlusion after cerebral ischemia in rats." (PMID 34298896, 2021). "HMGB1 extracellular release in the brain has been observed after cerebral ischemia in fetal sheep and in neonatal rat brain after cerebral hypoxia-ischemia." (PMID 34867200, 2021). "After cerebral ischemia, damaged neurons from the ischemic core release neuromediators, DAMPs, high-mobility group box-1 (HMGB1) protein, and reactive oxygen species (ROS), which activate microglia and the NF-κB pathway." (PMID 35008440, 2021). "In cerebral ischemia, over-expression of HMGB1 in astrocytes promotes the repair of neurovascular units, while low expression of HMGB1 decreases the density of microvessels around the infarct and inhibits the repair of motor neurons." (PMID 33868221, 2021). "Herein, we summarize and review the research on HMGB1 in cerebral ischemia, focusing especially on the role of HMGB1 in hypoxic ischemia in the immature brain and in white matter ischemic injury." (PMID 33384585, 2020). "In this review, we summarize the research on HMGB1 in cerebral ischemia, especially focusing on the role of HMGB1 in HI in the immature brain and in white matter ischemic injury." (PMID 33384585, 2020). "At present, the key role of HMGB1 in cerebral ischemia has been widely accepted, but the specific mechanisms are not yet fully understood." (PMID 33384585, 2020). "Collectively, these results indicated that HMGB1 plays an important role in regulating autophagic pathways during cerebral ischemia-reperfusion." (PMID 33384585, 2020). "We also outline the possible mechanisms of HMGB1 in cerebral ischemia and the main strategies to inhibit HMGB1 pertaining to its potential as a novel critical molecular target in cerebral ischemic injury." (PMID 33384585, 2020). "In this review, we discuss the role of DAMPs, especially HMGB1, in NETosis in cerebral ischemia, with a focus on the role of HMGB1 in NETosis-mediated thrombosis." (PMID 32731558, 2020). "HMGB1 contributes to the pathogenesis of cerebral ischemia via mediating neuroinflammatory responses to cerebral ischemic injury." (PMID 33384585, 2020). "Accumulating scientific evidence suggests that HMGB1 exerts an important role in central nervous system diseases, particularly in cerebral ischemia." (PMID 33384585, 2020). "Western blotting measurement of HMGB1 content in the core areas of brain ischemia revealed a dramatic decrease in HMGB1 in the core region, while immunohistochemical studies strongly suggested the release of HMGB1 from neurons in severely injured areas." (PMID 33321691, 2020). "Further investigations reveal that higenamine suppresses expression of high mobility group box-1 (HMGB1), which plays an important role for promoting inflammation in brain ischemia." (PMID 31213577, 2019).
Cerebral ischemia (continued). "Several studies have demonstrated that HMGB1 can be transferred from the nucleus of the neuron to the cytoplasm or released extracellularly by stimulation such as brain ischemia and subarachnoid hemorrhage." (PMID 31920543, 2019). "In conclusion, UA attenuated inflammatory cytokine production to protect the brain against cerebral ischemia and reperfusion injury in a rat model possibly through HMGB1/TLR4/NFκB signaling pathway activation." (PMID 29867706, 2018). "GL can specifically bind to HMGB1 and inhibit its activity, and it was used to protect the brain by inhibiting the inflammatory response after cerebral ischemia." (PMID 30013568, 2018). "GL is a direct HMGB1 inhibitor and the effective dose for treating cerebral ischemia and reperfusion injury has been established." (PMID 29867706, 2018). "We provide novel evidence that UA reduces inflammatory cytokine production to protect the brain from cerebral ischemia and reperfusion injury possibly through the HMGB1/TLR4/NFκB signaling pathway." (PMID 29867706, 2018). "In the animal model of cerebral ischemia, circulating HMGB1 acting via the receptor of advanced glycation end-products (RAGE) was responsible for the reduced secretion of TNFα and IL-12 by monocytes and lymphopenia." (PMID 29669581, 2018). "Recent studies have shown that reactive astrocytes release HMGB-1, which promotes neurovascular recovery after cerebral ischemia in mice." (PMID 26115623, 2016). "High mobility group box 1 (HMGB1) and peroxiredoxin (Prx) family proteins are two relevant DAMPs involved in brain ischemia." (PMID 27898011, 2016). "In animal models of experimental brain ischemia, the nuclear-derived DAMP high mobility group box 1 (HMGB1) has been linked to the development of CNS injury-induced immune suppression." (PMID 26594196, 2015). "The present study demonstrated that the predominantly nuclear HMGB1 staining of neurons in rats from the sham group weakened and disappeared during cerebral ischemia." (PMID 24594628, 2014). "Edaravone rescues rats from neuronal death after cerebral ischemia by attenuation of the release of HMGB1 from neuronal cells in the rat MCAO model." (PMID 23880849, 2013). "Inhibition of the up-regulation of HMGB1 and NF-κB at the early stage brings great benefits to cerebral ischemia." (PMID 23414442, 2013). "In the pathophysiology of cerebral ischemia-reperfusion, HMGB1 is released from neurons early following ischemic injury, and acts as a mediator linking acute brain damage and subsequent inflammatory processes." (PMID 22277256, 2012). "Taken together, these findings are consistent with a protective effect of α7nAChR-mediated inhibition of HMGB1 release after cerebral ischemia, and indicate that EA pretreatment can activate this protective pathway." (PMID 22277256, 2012). "Consistent with this, serum HMGB1 levels were significantly elevated in patients with cerebral ischemia, suggesting the potential role of this protein as a therapeutic target." (PMID 22277256, 2012). "Recently, studies have reported that atorvastatin downregulates the expression of HMGB1 in brain ischemia and inhibits HMGB1-induced vascular endothelial activation." (PMID 23226786, 2012). "Such endogenous danger molecules, so called DAMPs, have been noted after brain ischemia and include heat shock proteins (HSPs), hyaluronan, nucleic acids, and high mobility group box 1 (HMGB1)." (PMID 23097717, 2012). "It has been found that cerebral ischemia/reperfusion injury activates the HMGB1/TLR4 axis by inhibiting the expression of glutamate transporter (GLAST) in primary astrocytes, thereby decreasing glutamate clearance activity and increasing excitatory amino acid-mediated ischemic injury." (PMID 38740617, 2025).
Cerebral ischemia (continued). "In a 2-h MCAO rat model, administration of anti-HMGB1 monoclonal antibody immediately and 6 h later after cerebral ischemia–reperfusion had a reducing effect on infarct volume in both the cerebral cortex and striatum of rats, with reductions of 90% and 75% at 24 and 48 h, respectively." (PMID 38740617, 2025). "Considering that NETosis has been implicated in the exacerbation of inflammation, particularly in cerebral ischemia, HMGB1 might be directly or indirectly involved in inflammation in the post-PTS brains." (PMID 39910417, 2025). "Additionally, LDHA can promote HMGB1 expression and induce pyroptosis by upregulating H3K18la, thus exacerbating brain injury during cerebral ischemia-reperfusion." (PMID 40584617, 2025). "A recent study has found that microglial myeloperoxidase(MPO) -containing exosomes increase HOCl production in neighboring neurons and mediate disulfide HMGB1 translocation, thereby exacerbating neurological deficits in ischemic brain injury and cerebral ischemia/reperfusion injury." (PMID 38740617, 2025). "The results indicate that calycosin might offer protection against brain ischemia-reperfusion damage by blocking the HMGB1/NLRP3-driven pyroptosis mechanism in HAPI microglial cells." (PMID 40606597, 2025). "The present study revealed that hepcidin upregulation in hepatocytes may contribute to the elevation of serum hepcidin levels and systemic iron regulation after cerebral ischemia, with HMGB1 playing a key role." (PMID 39349828, 2024). "Interestingly, our study revealed a conversion of HMGB1 in the liver from its reduced form to its disulfide form following cerebral ischemia." (PMID 39349828, 2024). "A study on brain ischemia found that lactate upregulates HMGB1 expression by promoting histone lactylation of the HMGB1 promoter, which may lead to neuronal pyroptosis." (PMID 39876842, 2024). "Furthermore,we confirm that the anti-HMGB1-SA passes the blood–brain barrierin ischemic/reperfusion model rats and suppresses the immune and inflammatoryresponses of cerebral ischemia/reperfusion injury in vivo." (PMID 37844138, 2023). "The HMGB1/RAGE pathway is activated after cerebral ischemia." (PMID 37829255, 2023). "The results showed that EA and FPS-ZM1 could reduce the neural function score and neurons cell injury in cerebral ischemia rats by inhibiting the expression of HMGB1 and RAGE in primary motor cortex (M1) region." (PMID 37829255, 2023). "Thus, targeting the HMGB1/RAGE pathway holds promise as a therapeutic approach for cerebral ischemia." (PMID 37829255, 2023). "Calycosin might alleviate cerebral ischemia-reperfusion injury by inhibiting the HMGB1/TLR4/NF-κB pathway." (PMID 37528661, 2023). "Many studies have revealed that the inflammatory response plays a key role in the pathophysiology of cerebral ischaemia‒reperfusion injury, and the activation of the HMGB1/TLR4/NF-κB signaling pathway has been found to be involved in cerebral ischemia-induced inflammation." (PMID 37528661, 2023). "The present study shows that HMGB1 released by damaged neurons during the acute phase of cerebral ischemia induces the upregulation of hepcidin in astrocytes, which in turn induces intracellular iron accumulation in neurons and causes ferroptosis in the postischemic brain." (PMID 37907744, 2023). "Previous studies using neutralizing antibodies to HMGB1 or its antagonists have indicated that extracellular HMGB1 is crucial for neuroinflammation and concomitant neuronal damages in animal models of neurological disorders and brain ischemia." (PMID 37443823, 2023). "Therefore, in this study, we started the administration of Hp 24 hours after cerebral ischemia when systemic HMGB1 levels began to increase and examined the protective effects of Hp in the brain." (PMID 35243897, 2022).